CRBN (cereblon)
Diseases named in the same sentence as CRBN in open-access papers (continued):
Sharing a sentence is not in itself a finding about the gene and the disease.
myeloma (continued). "In summary, the IMiD-based therapy affected the prognosis of myeloma in patients with high CRBN expression; however, it did not affect the prognosis of patients with low CRBN expression." (PMID 34336672, 2021). "Recent studies showed that IMiDs bind to cereblon (CRBN), a substrate receptor of the CRL4–CRBN complex, to induce the ubiquitination and degradation of IKZF1 and IKZF3 in MM cells, contributing to their anti-myeloma activity." (PMID 34207079, 2021). "Several CRBN isoforms produced by alternative mRNA splicing are reported in multiple myeloma and standardized RT-PCR methods have not been proposed yet." (PMID 34336672, 2021). "Although deletion of Cereblon (CRBN), a target of iMiDs linked with interferon regulatory factor 4 (IRF4), has been associated with iMiD resistance in myeloma, the mechanism of iMiD resistance in PCNSL has not yet been clarified." (PMID 33957995, 2021). "In that work, we also revealed that IMiDs can prevent CRBN from ubiquitination and subsequent degradation, leading to the increased CRBN protein level and enhanced CRL4CRBN E3 ligase activity, contributing to the anti-myeloma effect of IMiDs." (PMID 33392195, 2020). "ATO and Lena exhibited independent non-interfering effects where ATO sensitized myeloma cells to Lena via the upregulation of cereblon expression, a major target for Lena, resulting in apoptosis." (PMID 32883022, 2020). "Two previous studies demonstrated that VHL-CRBN heterodimerizing PROTACs promote CRBN degradation, but not VHL degradation, and that treatment with these PROTACs causes resistance of multiple myeloma cells to IMiDs31,32." (PMID 31873151, 2019). "Binding of thalidomide to CRBN was shown to inhibit CUL4A-dependent E3 ligase activity, and thalidomide promoted CRBN-dependent degradation of specific transcription factors that play a critical role in B cell malignancies including myeloma." (PMID 29746508, 2018). "Recently, lenalidomide, a CRBN/RBX1 inhibitor, has shown protective roles in multiple COVID-19–infected myeloma patients against progression into severe infections, which suggests the emergence of this particular platelet subpopulation may drive the disease severity in COVID-19 infection." (PMID 41066207, 2025). "Recently, Lenalidomide, a CRBN/RBX1 inhibitor, has shown protective roles in multiple COVID-19 infected myeloma patients against progressing into severe infections, and suggests the emergence of this particular platelet subpopulation may drive the disease severity in COVID-19 infection." (PMID 39764102, 2024). "In addition, IL-2 and TNF-α secretion was reduced in T cells co-cultured with a human myeloma cell line with CRBN knockout compared to those without CRBN knockout." (PMID 38004369, 2023). "In the context of multiple myeloma, thalidomide and its derivate pomalidomide could promote the degradation of Ikaros by altering the substrate specificity of cereblon (CRBN), the target of the CUL4-RBX1-DDB1-CRBN (also known as CRL4CRBN E3 ubiquitin ligase." (PMID 37566057, 2023). "Thalidomide and its analogs lenalidomide and pomalidomide directly bind to the cereblon (CRBN) and subsequently recruit neo-substrates IKZF1/3 to the CRL4CRBN E3 ligase, thereby inducing ubiquitination and degradation of IKZF1/3 and exhibiting an anti-myeloma effect." (PMID 35321428, 2022). "Moreover, the most appropriate testing method for measuring CRBN expression is not confirmed in the multiple myeloma patients." (PMID 34336672, 2021). "However, the cleavage of CRBN can be induced by CASP-8 activation, which could be mediated by Len in myeloma cells, and the stability of the cleaved CRBN is reduced." (PMID 33392195, 2020). "It has been shown that a lack of CRBN could induce a resistance to these drugs in multiple myeloma and B cell lymphoma." (PMID 29348877, 2017).
myeloma (continued). "Binding lenalidomide or its analogues, thalidomide and pomalidomide, to CRBN would increase the binding of IKZF1 (Ikaros) and IKZF3 (Aiolos) proteins to the CRBN-based E3ULC, leading to increased ubiquitination and consequent degradation, which is toxic to myeloma cells." (PMID 24687382, 2014). "However, 21 % RRMM and 25 % NDMM patients did not respond to the LD and TD regimen, respectively, despite expression of CRBN protein within the myeloma cells, suggesting the possibility of mechanisms of resistance that do not involve CRBN." (PMID 24687382, 2014). "However, CRBN was not required for bortezomib-induced apoptosis in multiple myeloma." (PMID 35321428, 2022). "This issue could be overcome by either hijacking two different E3 ligases, CRBN and VHL, or a PROTAC, such as YKL-06-102, that simultaneously targets IKZF1, IKZF3, and CDK6, achieving intramolecular synergistic effects even in IMiD-insensitive multiple myeloma cells." (PMID 35197447, 2022). "Thus, TC11 exerts its anti-myeloma effect via molecular interactions which do not involve CRBN." (PMID 25617756, 2015). "Low CRBN expression levels were detectable in CD138 negative cells, representing non-myeloma cells within a BM microenvironment, which may result in a misinterpretation of the CRBN gene expression level if the sorting of CD138 positive myeloma cells is not sufficiently pure." (PMID 24687382, 2014).
Intellectual disability (17 papers, 2011 to 2025). "In 2010, a breakthrough study identified that thalidomide binds to a protein called cereblon, linked to a crucial gene for mental retardation." (PMID 36966238, 2023). "CRBN appears to play a role in nervous system development during embryogenesis, as mutations of the CRBN gene result in mental retardation." (PMID 36991452, 2023). "Mutations in the cereblon gene is associated with mental retardation, compromising cognitive processes and memory." (PMID 36966238, 2023). "Another missense mutation in CRBN is also associated with severe intellectual disability and seizures." (PMID 33777938, 2021). "Before CRBN was identified as the protein target of IMiDs, a CRBN germline nonsense mutation was implicated in an autosomal recessive form of mental retardation." (PMID 34834536, 2021). "Cereblon (Crbn), which was originally identified as a gene associated with intellectual disability, is a component of the CRL4CRBN E3 ubiquitin ligase." (PMID 33127885, 2020). "It is clear, however, that cereblon and IKZF1/3 are expressed within the brain and are associated with learning and memory, with mutations in cereblon posing a risk for intellectual disabilities." (PMID 31867326, 2019). "Thalidomide acts on cereblon (Crbn), a gene on human chromosome 3p26.3 that causes intellectual disability in humans when mutated, and leads to inhibition of CRL4CRBN E3 ubiquitin ligase-related functions." (PMID 30518785, 2018). "Intellectual disability (ID), one of the most common human developmental disorders, can be caused by genetic mutations in Cullin 4B (Cul4B) and cereblon (CRBN)." (PMID 29370161, 2018). "Some candidates have been linked to intellectual disability (ID), such as CRBN, GPKOW, HERC1 and KCNA4, or to other behavioral disorders, such as CDC42EP4 and SLITRK5." (PMID 30102725, 2018). "However, the significance of these mutations with respect to intellectual disability and cellular functions of CRBN is still unclear." (PMID 33777938, 2021). "The physiological significance of the zinc finger is still unknown, but it is noteworthy that the C391R mutation of CRBN was reported to be associated with intellectual disability." (PMID 32414180, 2020). "Mutations in KDM5C and CRBN resulted in intellectual disability, which suggested a possible correlation between KDM5C and CRBN." (PMID 39881283, 2025). "CRBN or Cereblon (FDR=0.003) is known to play a role in memory and learning and it has been previously associated with mental retardation." (PMID 33892787, 2021). "It is well known that cereblon is a key protein in autosomal recessive nonsyndromic mental retardation." (PMID 28894755, 2017). "However, the possible functions of KDM5C and CRBN in intellectual disability need to be further investigated." (PMID 39881283, 2025). "CRBN was originally identified as a gene responsible for mild intellectual disability in humans." (PMID 33777938, 2021). "The function of CRBN was unknown at the time, although it was thought to be related to mental retardation and intellectual disability." (PMID 32414180, 2020). "Recently, the molecular mechanisms of CRBN-related intellectual disability have been elucidated." (PMID 30518785, 2018). "The normal CRBN function is cytoprotective against UPS dysfunction-induced cell death and the defect may be of great importance to intellectual disability (ID) pathogenesis." (PMID 28894755, 2017). "In addition the CHL1 gene, mapping at 3p26.3 distally to CRBN and CNTN4, was proposed as candidate gene for a non specific mental retardation because of its high level of expression in the brain." (PMID 21457564, 2011).
acute myeloid leukemia (11 papers, 2015 to 2026). Acute myeloid leukemia (AML) is a group of neoplasms arising from precursor cells committed to the myeloid cell-line differentiation. "Additional analyses reveal ZMYM2 and ZMYM2-FGFR1 fusion protein—responsible for the 8p11 syndrome involved in acute myeloid leukaemia—as CRBN neo-substrates." (PMID 35013300, 2022). "The tumor type that included more targets was Acute Myeloid Leukemia (AML) where CRBN and VHL were the most frequently expressed ligases." (PMID 35249548, 2022). "CC-90009 is a next-generation cereblon E3 ligase modulating agent selective for eRF3a and capable of inducing apoptosis in AML (acute myeloid leukemia) cells." (PMID 37917619, 2023). "SD-91, the CRBN E3 ligase-based STAT3 PROTAC, led to complete tumor regression in mouse xenografts of MOLM-16 acute myeloid leukemia (AML)." (PMID 39872303, 2023). "It induces CRBN-dependent degradation of BET family proteins, including BRD2, BRD3, and BRD4, in human acute myeloid leukemia (AML) cells with a DC50 of 100 nM." (PMID 40507351, 2025). "The CRBN‐based dAurA383 preferentially degrades the highly abundant mitotic AURKA, while cIAP‐based dAurA450 degrades the lowly abundant interphase AURKA in acute myeloid leukemia (AML) cells." (PMID 35652200, 2022).
myelodysplastic syndrome (8 papers, 2016 to 2025). A clonal hematopoietic disorder characterized by dysplasia and ineffective hematopoiesis in one or more of the hematopoietic cell lines. "Amongst these CRBN neosubstrates, CK1α is ubiquitinated and degraded in the presence of lenalidomide, which leads to attenuation of the growth of myelodysplastic syndrome with deletion of chromosome 5q." (PMID 35780831, 2022). "This class of small molecules acts as a bridge between CRBN and a set of neosubstrates required for the growth of hematologic tumors, such as multiple myeloma and myelodysplastic syndrome." (PMID 35780831, 2022).
breast carcinoma (7 papers, 2019 to 2025). "Poorer OSs were associated with patient groups with low CRBN expression in breast cancer (HR = 0.45, p = 6.8 × 10−0.7) and lung cancer (HR = 0.39, p < 1 × 10−16)." (PMID 33916291, 2021). "First, the OS of breast cancer and lung cancer patients were positively correlated with CRBN expression according to the microarray-based database of the KM plotter." (PMID 33916291, 2021).
prostate carcinoma (7 papers, 2021 to 2025). A carcinoma that arises from epithelial cells of the prostate gland. "We found that CWR22Rv1 cells express lower level of CRBN compared with VCaP and other AR-positive prostate cancer cell lines, which may account for the higher DC50 observed in CWR22Rv1." (PMID 41237749, 2025). "In a prostate cancer model, castration-resistant prostate cancer (CRPC) cells transformed into NE-like cancer upon repeated enzalutamide treatment exhibited increased DNA accessibility at the CRBN promoter region—comparable to that observed in the H660 NEPC cell line." (PMID 40551250, 2025).
lung carcinoma (6 papers, 2021 to 2025). "In this paper, the mechanism of down-regulation of T cells leading to resistance of PD-1 antibody in lung cancer, the mechanism of CRBN regulating T cells, and research progress of CRBN regulator in the treatment of lung cancer were reviewed." (PMID 33478191, 2021). "Investigation of CRBN-expression phenotypes and related pathways in stage 4 cancer could reveal the role of CRBN in late stage of lung cancer and provide supportive evidences for the clinical use of CRBN and CRBN-related pathways as therapeutic target or prognostic marker for stage for patients." (PMID 33916291, 2021). "For instance, high expression of E3 ligase CRBN is reported in lung cancer, thus ligands for CRBN (lenidomide, thalidomide, pomalidomide) should be installed in the PROTAC model to develop an anti-lung cancer therapeutic." (PMID 33840388, 2021). "Moreover, significantly higher expression levels of CRBN and DDB1 mRNA were detected in NE lineage lung cancers compared to non-small cell lung cancers (NSCLC), which are representative of non-NE cancers in the lung." (PMID 40551250, 2025). "Overexpression of CRBN in non-NE lung cancer cell lines enhanced GSPT1 degradation kinetics and significantly increased sensitivity to CYRS381." (PMID 40551250, 2025). "The ectopic expression of RPMA or RPMN in non-NE lung cancer cell lines (H2023 and HCC827) consistently elevated CRBN and DDB1 expression across all clones achieved, regardless of their basal genetic backgrounds." (PMID 40551250, 2025). "These cell lines exhibited significantly higher levels of CRBN and DDB1 protein compared to non-NE lung cancer cell lines." (PMID 40551250, 2025).
leukemia (5 papers, 2015 to 2025). A malignant (clonal) hematologic disorder, involving hematopoietic stem cells and characterized by the presence of primitive or atypical myeloid or lymphoid cells in the bone marrow and the blood. "The results were consistent with the findings in HEK293T cells that KDM5C stabilized CRBN in leukemia cells." (PMID 39881283, 2025). "A PROTAC for MDM2, for example, consists of a nutlin-based MDM2 ligand joined to the E3 ubiquitin ligase cereblon (CRBN; CRL4CRBN) via a short linker and promotes efficient degradation of MDM2 in leukemia cells." (PMID 33825941, 2021). "To determine if this difference in essentiality is reflected in differential resistance acquisition, we focused on two BET Bromodomain targeting PROTACs: dBET6 (CRBN-based) and ARV-771 (VHL-based) that have matched cellular potency, including in the near-haploid human leukemia cell line KBM7 26,27." (PMID 36329119, 2023).
Alzheimer disease (4 papers, 2021 to 2024). A progressive, neurodegenerative disease characterized by loss of function and death of nerve cells in several areas of the brain leading to loss of cognitive function such as memory and language. "Furthermore, CRBN-KO mice show a resilient phenotype towards stress and the pathological aggregation of Tau, a hallmark of tauopathies as Alzheimer’s disease." (PMID 38514794, 2024). "Accordingly, we suggest that CRBN may serve as a potential target for enhancing homeostatic sleep pressure to treat insomnia and decreasing pathologic proteins to prevent neurodegenerative diseases, such as Alzheimer’s disease and Parkinson’s disease." (PMID 39349747, 2024).
chronic lymphocytic leukemia (4 papers, 2016 to 2025). "Many recent studies reported also the role of CRBN in IMiDs response in vitro and in vivo in patients with MM, chronic lymphocytic leukemia, or MDS." (PMID 29780393, 2018). "Meanwhile, lenalidomide was found to have inhibiting function of tumor growth through PI3K/Akt pathway, cereblon/p21, cyclin D1/p27 and Bcl-2 in chronic lymphocytic leukemia (CLL) and mantle cell lymphoma (MCL) in pre-clinical experiments." (PMID 27009084, 2016). "This agent hijacks the CRBN-dependent ubiquitin-proteasome system to induce BTK degradation—a pivotal regulator of B-cell activity whose inhibition ameliorates B-cell malignancies (e.g., chronic lymphocytic leukemia [CLL]) and autoimmune disorders (e.g., graft-versus-host disease)." (PMID 41220927, 2025).
glioma (4 papers, 2018 to 2025). A benign or malignant brain and spinal cord tumor that arises from glial cells (astrocytes, oligodendrocytes, ependymal cells). "Glioma cell lines harbouring CRBN mutations record density-dependent decrease of BK currents, which can be restored by blocking Cullin ubiquitin ligase activity." (PMID 29370161, 2018). "Endogenous Slo1 level was also decreased after CRBN was knocked down by RNAi or knocked out by CRISPR-Cas9 gene editing in glioma cells." (PMID 29370161, 2018). "Likewise, treatment with proteasome or neddylation inhibitors (MG132, bortezomib or MLN4924) in CRBN KO glioma cells could also increase the Slo1 levels, though treatment with bortezomib or MLN4924 in WT cells for excessive time led to decreased Slo1 levels, likely due to compound cytotoxicity." (PMID 29370161, 2018).
melanoma (4 papers, 2020 to 2025). A malignant, usually aggressive tumor composed of atypical, neoplastic melanocytes. "The CDK9 PROTAC THAL-SNS-032 depleted cellular levels of CDK9 (and partly also other CDKs) in hESCs already at 1 μM concentration, presumably due to higher expression of CRBN ubiquitin ligase in hESCs compared to A375 melanoma." (PMID 32934219, 2020). "Interestingly, Cereblon/CRBN-deficient T cells resulting in AIOLOS reduced degradation/increased expression, exert a more efficient antigen-specific cytosolic activity against melanoma cells both in vitro and in vivo." (PMID 34694366, 2021). "Besides all three IAPs, 98 induced the degradation of the melanoma inhibitor of IAP (ML-IAP) highly expressed in melanoma cell lines while the CRBN level was not changed." (PMID 37667522, 2023).
neuroblastoma (4 papers, 2016 to 2025). Neuroblastoma (NB) is the most common solid, extracranial childhood tumor. "To specify the mitochondrial role of CRBN, we mitochondrially expressed CRBN in human neuroblastoma SH-SY5Y cells." (PMID 27417535, 2016). "In the GI-ME-N neuroblastoma cell line, ASCL1 overexpression led to increased H3K27ac signals around the CRBN promoter region, suggesting transcriptional activation." (PMID 40551250, 2025).
anemia (3 papers, 2018 to 2025). A reduction in the number of red blood cells, the amount of hemoglobin, and/or the volume of packed red blood cells. "Factors with significant impact on median PFS included grade of anemia before treatment and presence of both examined polymorphic variants of CRBN gene." (PMID 29844872, 2018). "In addition, our analysis revealed that a higher CRBN serum ratio between LD initiation and BR (≥1.37) was significantly associated with anemia and earlier relapse to LD, suggesting that an increase in circulating CRBN may reflect disease progression or tumor stress." (PMID 40650115, 2025).
colon cancer (3 papers, 2021 to 2023). "Interestingly, a study comparing VHL and CRBN dependencies in diverse tumor types concluded that VHL-based PROTACs can induce degradation in a broader number of cell lines, as CRBN was frequently found inactivated or expressed at low levels in lung and colon cancer lines." (PMID 36765568, 2023).